MYC (MYC proto-oncogene, bHLH transcription factor)
Diseases named in the same sentence as MYC in open-access papers (continued):
Sharing a sentence is not in itself a finding about the gene and the disease.
cancer (continued). "Pan-cancer studies have revealed a higher frequency of recurrent alterations in cancer driver genes, including PIK3CA, APC, PTEN, and MYC, and higher overall burden of copy number alterations, including whole genome duplication in metastases compared with primary tumors." (PMID 39416100, 2025). "According to our preclinical findings, patients who did not respond to PARPis had a significantly higher MYC signature in PANCK+ cancer cells than responders." (PMID 41273720, 2025). "In comparison with human cancer cell lines which usually have multiple genetic defects, the ABC-Myc cell lines have a simpler genotype (MYC alone as a driver), which may be less impacted by epistasis when used for genome-wide Identification of fitness genes." (PMID 38853928, 2025). "For experimental validation, we chose the MYC TAD because chromatin interactions between the MYC promoter region and various cell type-specific super enhancers (SEs) within this TAD have been thoroughly characterized across many common cancer cell lines." (PMID 41335466, 2025). "We used RT-PCR primers specific for CircPVT1 to demonstrate that it was significantly more abundant in cancer cell lines with MYC/PVT1 genomic rearrangements (MYC/PVT1 gain + PVT1 translocation, COLO-320DM, SK-PN-DW, and D458) compared to MYC/PVT1 neutral cell lines (U2OS, BxPC-3, and DU145)." (PMID 40027648, 2025). "Furthermore, given that the first successful phase 1 clinical trial for MYC inhibitor (OMO-103) was recently published, our results suggest a potential impact for combined therapies for cancer that include radiation and MYC inhibition." (PMID 40180576, 2025). "Moreover, FoxM1 can upregulate the expression of cancer stemness genes, such as BMI1, NANOG, and c-MYC, in HCC cells." (PMID 40050970, 2025). "Further, B vitamins could also interact with oncogenic regulators such as HIF-1α, MYC, and AMPK, which influence cancer cell metabolism." (PMID 40076592, 2025). "The inhibitory effect was also observed in cancer cells where treatment with EGCG reduced binding of c-MYC to TBP, but not to its obligate partner MAX, which binds to the C terminus of c-MYC." (PMID 40406608, 2025). "In addition to c-MYC, other pluripotency factors such as OCT4, SOX2, NANOG, and KLF4 are known to act as potent cancer drivers." (PMID 40541178, 2025). "Another marker expressed in a myriad of different cancers, ALDH1, might prove a useful therapeutic target due to its roles in modulating MYC, VEGF, and Wnt/β-catenin signaling pathways, and in conferring protection from ROS." (PMID 39859345, 2025). "In this research, it was also found that MYC might play an important role in the anti-cancer effect of ART on BLCA, and ART had a strong binding affinity for MYC." (PMID 40303931, 2025). "While the detailed mechanism by which FFX sensitizes AKT/mTORC1/MYC axis needs to be investigated, the targeting of FFX emerges as a promising therapeutic strategy for MYC-dependent cancers, offering a potential avenue for combating the otherwise elusive direct inhibition of MYC." (PMID 40027648, 2025).
cancer (continued). "To model molecular interactions in sufficient complexity, we used ModCellTM, a mechanistic model based on cancer-related signaling pathways such as the Hedgehog, Wnt, RAS/MAPK, and PI3K/AKT/MTOR signaling, that either enhance MYC transcriptional activity or suppress apoptosis via effector caspases." (PMID 40968384, 2025). "Given our findings that PA2G4 and c-MYC form a positive forward feedback expression loop in MYC- and MYCN-driven cancers, we hypothesized that WS6 would repress the expression of both proteins in c-MYC-driven malignant cells." (PMID 41002386, 2025). "Based on the in silico prediction models, SPR data and competitive inhibition shown by ELISA, we suggest that rLon and its domains inhibit MYC/MAX complex formation, which would explain the potent inhibition of MYC-dependent gene expression in rLon-treated mice with cancer or infection." (PMID 40000737, 2025). "Since drugs targeting CXCR2 have failed to prove effective in the clinic, we reasoned cancer cells expressing high levels of HIF1A or MYC are resistant to CXCR2 inhibitors." (PMID 40050422, 2025). "Finally, ddPCR assays showed that the expression of c-MYC target genes was decreased in PDTOs exposed to EM127, confirming that SMYD3 plays an important role in cancer stemness features also in this complex cellular model." (PMID 40588481, 2025). "While in non-cancerous cells, MYC expression is tightly controlled, and its dysregulation in cancer cells drives proliferation and decreases the apoptosis rate." (PMID 40227591, 2025). "The double knockdown of YY1 and MYC resulted in a significant decrease in the cancer score to 0.056, corresponding to the disappearance of the cancer attractor and the emergence of dominant normal and near‐normal attractors in the landscape." (PMID 39840939, 2025). "One notable example is the clinical trial agent APTO-253, which effectively inhibits c-MYC expression in various cancer cell lines, including those from colon cancer, leukemia, non-small-cell lung cancer, renal cancer, and prostate cancer." (PMID 40333779, 2025). "Based on this, MYC is not only a downstream regulator of oncogenesis affected by TEAD activation, but can also play an important role in YAP/TAZ-TEAD signaling leading to cancer progression." (PMID 41347094, 2025). "Along with the current study, the link between HSF1 and MYC has been seen in cancer cells and non-cancer cells, suggesting that their interaction is physiologic but can be co-opted in cancer cells." (PMID 39831777, 2025). "The combination of direct MYC inhibition with DDR-targeting agents now moves from conceptual rationale to a concrete translational opportunity, preparing the stage for this novel therapeutic duo across multiple cancer contexts." (PMID 41561634, 2025). "Indeed, deregulated MYC activity may be linked to most - if not all - human cancers." (PMID 39972241, 2025). "Similar to the effect seen when culturing soft ECMs, treatment with JAK inhibitor I prevented MYC expression in cells cultured on stiff ECMs, suggesting that stiff ECMs may activate the JAK-MYC-ATF5 axis in cancer cells." (PMID 40124511, 2025). "• Exertion of anticancer effects through 3 major pathways: apoptosis (BIRC3, BIRC5, caspase-8, caspase-9, and PARP1), transcriptional dysregulation in cancer (CDKN1A, CDKN1B, MMP9, MYC, JUN, and RELA), and cancer progression (caspase-3, CCND1, CTNNB1, VEGFA, and Wnt-1)." (PMID 39181121, 2025). "A selective and specific MYC inhibitor has been generated which exhibits a strong in vivo anti-cancer property, and synergizes with immunotherapy without exerting toxicity." (PMID 40282551, 2025). "Interestingly, central carbon metabolism in cancer (HK2, MAPK3, MYC, PFKP, PKM2, SLC16A3), galactose metabolism (B4GALT2, HK2, PFKP) and fructose and mannose metabolism (HK2, PFKFB4, PFKP) are associated with metabolism." (PMID 39924557, 2025).
cancer (continued). "We also reasoned that loss of the residual PVT1ts in cells with MYC/PVT1 gain + PVT1 translocation, or cells with MYC/PVT1 gain without PVT1 translocation, would further augment MYC expression and contribute to increased aggressiveness in these cancer cells." (PMID 40027648, 2025). "Furthermore, CHRDL2 was found to differentially impact several key cancer pathways, including the EMT pathway, MYC, MTOR, PI3/AKT and RAF." (PMID 40434957, 2025). "It is therefore tempting to speculate that at least in some cancers, GCN2 has a direct or indirect inhibitory effect on MYC, potentially through regulation of one of MYC’s multiple partners." (PMID 40032489, 2025). "Large-scale genetic screens have explored noncanonical sensitivities in MYC-driven cancers, and the range of potential synthetic lethal targets is expanded." (PMID 40290126, 2025). "MYC dysregulation is a key event in these cancers, but overexpression of MYC alone is not always enough to cause cancer." (PMID 40027648, 2025). "Our findings reveal a previously unknown role of TCF4 in recruiting factors that enhance MYC activity to CRC heterodimerization partners and a novel understanding of TCF4's function in development and cancer." (PMID 39119816, 2025). "Furthermore, the MYC, DDX21, USP7, RFC4, APEX1, CDK9, and NOP2 of the “cancer cells_vs_all-PDAC” group play a critical role in the metabolic reprogramming of the PDAC, contributing to the poor prognosis of PDAC." (PMID 40906153, 2025). "MYC activates angiogenesis by increasing the expression of interleukin (IL)-1β, as well as by inhibiting thrombospondin-1 (TSP-1), which facilitates nutrient delivery to the cancer cells." (PMID 40290126, 2025). "Simultaneous PP2A activation and importin inhibition reduces nuclear levels of proteins that drive cancer progression and therapeutic resistance such as JUN, YAP, MYC, androgen receptor, hnRNPA1, and NF-κB under conditions where compounds that target PP2A or KPNB1 individually are inactive." (PMID 40588551, 2025). "The senolytic compound Dasatinib, which suppresses anti-apoptotic signaling by interfering with the activity of several protein kinases, efficiently and selectively eliminated GNE/BMS-treated senescent KRASG12V/MYC cancer cells, but not the control cells." (PMID 40550880, 2025). "This firmly suggests that the FFX protein, not the RNA, has the capacity to enhance MYC levels in these cancer cells." (PMID 40027648, 2025). "According to the model, a high MYC activity in cancer cells leads to a high secretion of miR-105 to activate MYC signaling in stromal cells, phenotypically extending the effects of MYC originating from cancer cells to non-cancer cells." (PMID 39834935, 2024). "We report the development of mRNA overwriting therapy based on the engineered destabilization of the poly U stabilizing elements on the 3′UTR of MYC, which triggered nonsense-mediated decay to degrade the MYC transcript and protein, leading to the inhibition of c-MYC-driven TNBC and other cancers." (PMID 39123391, 2024). "Since MYC positively regulates PD-L1 expression as a transcription factor, we hypothesize TRMT61A may play a role in OV therapy cancer immune evasion by promoting reactive PD-L1 expression through enabling efficient MYC synthesis." (PMID 38730256, 2024). "In this study, we identified that MYC, which plays critical roles in tumorigenesis and therapeutic resistance 20, was highly expressed in a cisplatin-resistant patient-derived xenograft (PDX) model of HNSCC and regulates cancer stemness." (PMID 38169606, 2024). "Interestingly, cancer cells that were low in NMT2, highly dependent on NMT1, or predicted to be sensitive to NMTI treatment (high MISS-54 score) showed high MYC expression." (PMID 38715059, 2024).
cancer (continued). "As reported in cancer and stem cells, “hockey stick” plots showed that H3K27ac signals were asymmetrically distributed across the genome, with disproportionately higher density at super-enhancers of T-ALL genes like MYC, TCF, ERG, and ETV640." (PMID 38352301, 2024). "Importantly, ICN1-driven T-ALL exemplifies a cancer with high BRD4 dependency wherein BRD4, cooperatively with ICN1 and MYC, drive expression of key T-ALL genes in a positive feed-forward loop to establish the leukemogenic program." (PMID 38352301, 2024). "YBX1 has predictive value for drug resistance and poor prognosis in more than 20 cancer types, and upregulates the expression of multiple drug resistance genes, including ABCB1, MVP/LRP, TOP2A, CD44, CD49f, BCL2, and MYC, upon UV irradiation or Cisplatin treatment." (PMID 39168971, 2024). "MYC KO led to a rapid decrease in mitochondrial mass, structural integrity, and function, along with the degradation of respiratory complex I, suggesting a higher OXPHOS dependency in MYC-driven cancer cells." (PMID 38715059, 2024). "Stemness, known as the self-renewal capacity of cancer stem cells, is regulated by many signaling pathways, including TGF-β, Hedgehog, Wnt, Notch, and FGF, and transcription factors, including NANOG, OCT4, SOX2, KLF4, and c-MYC." (PMID 39516821, 2024). "Since cancer cells dynamically undergo metabolic remodeling during drug treatment, how BET inhibition induces MYC-dependent or independent metabolic adaptations in cancer cells remains unclear." (PMID 39872506, 2024). "The GAC isoform is more frequently upregulated in cancer cells than KGA, and has been shown to be regulated by MYC, leading to a ‘glutamine addiction’ phenotype in MYC-driven tumors." (PMID 38488852, 2024). "Consistently, STK16 overexpression enhanced the proliferation ability of cancer cells in c-MYC WT cancer cells, but not in c-MYC S452A cancer cells." (PMID 38622518, 2024). "Using the “Cancer stem cells”, we analysed the association between the copy-number estimates of the 9 MCR regions and the expression status of MYC separately visualising cells with and without MCR loss events." (PMID 38877600, 2024). "Of note, MCL1 is an essential anti-apoptotic gene involved in c-MYC-driven cancer development, and the synergy of MCL1 with c-MYC overexpression could suppress c-MYC-driven apoptosis and trigger liver tumor development." (PMID 39062197, 2024). "Patient-derived cancer stem cells (CSCs) from glioblastoma or acute myeloid leukemia have strong circadian rhythms irrespective of the elevated MYC expression levels, which is consistent with both experimental tumor models." (PMID 38892035, 2024). "Thus, these miRNAs either positively or negatively affect cancer progression by targeting both cancer cells per se and the cancer microenvironment via modulation of all three of SP1, MYC, and HIF1A." (PMID 39590335, 2024). "NEAA proline can be synthesized by aldehyde dehydrogenase family 18 member A1 (ALDH18A1, P5CS) and pyrroline-5-carboxylate reductase (PYCR) from glutamine and arginine, thus MYC induced P5CS and PYCR upregulation can promote the proliferation and invasion of cancer cells." (PMID 38218942, 2024).
cancer (continued). "This suggests that the oncogenic drivers may influence the pathway for de novo polyamine synthesis, with MYC-driven cancers potentially preferring arginine as a precursor and KRAS-driven cancers preferring glutamine." (PMID 38761252, 2024). "The interplay between ERBB2 and its direct targets MYC, PTEN, and BCL2 creates a robust network that collaboratively impacts cancer cell biology by promoting proliferative signaling, evading growth suppressors, resisting cell death, and facilitating invasion and metastasis." (PMID 39409883, 2024). "Furthermore, MYC overexpression contributes to mitochondrial biogenesis and enhances OXPHOS, enabling cancer cells to adapt to metabolic stress and nutrient deprivation." (PMID 39408832, 2024). "There are no approved direct clinical inhibitors of c-MYC, which is a significant biological and clinical challenge that needs to be overcome for more effective cancer treatment." (PMID 39123391, 2024). "Moreover, our study along with others are beginning to reveal that proto-oncogenes such as MYC and MYCN can regulate the methylation of splicing factors that provide cancer cells with a mechanism which promotes cell survival." (PMID 38049564, 2024). "These new findings explain why dual inhibition of SUMOylation and MEK induced dramatic antitumor responses in MYC-expressing KRAS-mutant cancer cells in vitro and in vivo without immune reactions." (PMID 38992694, 2024). "The three MYC paralogs (MYC, MYCN, and MYCL) are central players in normal development and tissue homeostasis, and when dysregulated, fuel many of the processes that are hallmarks of cancer." (PMID 39177021, 2024). "This precise targeting mechanism leads to the degradation of MYC protein through the ubiquitin E3-ligase STUB1-mediated 26S proteasome pathway, ultimately inducing apoptosis in cancer cells and highlighting its significant role in cancer treatment." (PMID 39075086, 2024). "The nCounter v2 Cancer CN Assay panel consists of 87 target genes and is intended for CNV genotyping of tumors with various profiles of aberrations in the PIK3CA, AKT, PTEN, BRCA, ERBB2, and MYC genes." (PMID 39409874, 2024). "To classify iCCA transcriptomic dysregulation in the context of cancer hallmarks, we performed gene set enrichment analysis (GSEA) and observed a highly significant enrichment of MYC targets among the upregulated genes, confirming the involvement of c‐MYC in cholangiocarcinogenesis." (PMID 38877653, 2024). "An important example of oncogenes with universal significance is the family of MYC transcription factors, which comprises c-MYC (called MYC hereafter), NMYC and LMYC.5 6 Several lines of experimental and clinical research suggest that MYC should be an outstanding cancer target." (PMID 38821858, 2024). "Likewise, mir-186 suppressed SP1, MYC, and HIF1A, and the induction of mir-186 induces the sensitivity of cancer cells to anticancer drug." (PMID 39590335, 2024). "Through in vitro assays, we also found that the absence of c-MYC S452 phosphorylation markedly inhibited the proliferation ability of cancer cells." (PMID 38622518, 2024). "Similar to other USP29 substrates c-MYC, HIF1α and Snail1, AURKB deregulation often occurs in cancers, implying that USP29 may become a potential target for cancer treatment." (PMID 38233848, 2024).